STAT3 (signal transducer and activator of transcription 3)
Diseases named in the same sentence as STAT3 in open-access papers (continued):
Sharing a sentence is not in itself a finding about the gene and the disease.
enteropathy-associated T-cell lymphoma (2 papers, 2024 to 2025). An uncommon mature T-cell lymphoma of intraepithelial lymphocytes. "The JAK1 and STAT3 gene mutations are observed in 90% of Enteropathy-associated T-cell lymphoma (EATL) patients and 80% of refractory celiac disease type II (RCD2) patients." (PMID 40046420, 2025).
enthesitis (2 papers, 2023 to 2025). Inflammation at the site of insertion of ligaments, tendons, and other fibrous structures into bone. "Notably, while prior research identified interactions between A20 and STAT3, the A20mye-KO model revealed STAT1, rather than STAT3, as the primary mediator of enthesitis." (PMID 41583484, 2025).
epithelial dysplasia (2 papers, 2022 to 2026). "By downregulating JAK2/STAT3 phosphorylation, KCs proliferation was inhibited and apoptosis was induced, which has therapeutic benefits for OLP epithelial dysplasia." (PMID 41983130, 2026).
Ewing Sarcoma Family Tumors (2 papers, 2007 to 2013). "Activation of Stat3 was reported to be present in Ewing sarcoma family tumors (ESFT)." (PMID 17598902, 2007).
Fanconi anemia (2 papers, 2021 to 2025). Fanconi anemia (FA) is a hereditary DNA repair disorder characterized by progressive pancytopenia with bone marrow failure, variable congenital malformations and predisposition to develop hematological or solid tumors. "Ouabain was able to inhibit DNA damage repair directly by the Fanconi anemia/BRCA pathway or indirectly by STAT3 inactivation, thus ouabain treatment could remarkably induce DNA double-strand breaks." (PMID 34277430, 2021). "Mechanistically, we show that NIF acts through the inhibition of STAT3, which we identify as a non-canonical transcription factor for Fanconi anemia genes." (PMID 40038300, 2025).
folate deficiency (2 papers, 2023 to 2025). A nutritional condition produced by a deficiency of FOLIC ACID in the diet. "Both HFF and folate deficiency significantly increased the phosphorylation of STAT3 and Smad2/3, suggesting synergistic effects of HFF−f on chronic renal inflammation and fibrosis." (PMID 37630806, 2023). "The positive correlation between leptin and phosphorylated STAT3 ratio, as well as TGF-β1 and phosphorylated Smad2/3 ratio in renal tissues, revealed the mechanisms of effects of the HFF diet and folate deficiency." (PMID 37630806, 2023). "Activation of these pathways by phosphorylated STAT3 and Smad2/3 were affected by both HFF diet and folate deficiency." (PMID 37630806, 2023).
fusariosis (2 papers, 2024 to 2025). "A recent report discussed a rare condition known as primary invasive cutaneous Fusariosis, which was observed in four patients with a specific genetic mutation called STAT3 dominant negative (DN)." (PMID 40317072, 2025). "These case reports offer valuable knowledge about the underlying mechanisms and treatment of primary invasive cutaneous Fusariosis in individuals with STAT3 DN mutations." (PMID 40317072, 2025). "The findings emphasize the need to consider primary invasive cutaneous Fusariosis as a potential diagnosis in patients with persistent skin lesions and underlying immune deficiencies, particularly those associated with STAT3 DN mutations." (PMID 40317072, 2025). "In this notable case study, a 14-year-old male with STAT3 autosomal dominant hyper-immunoglobulin E syndrome (STAT3 AD-HIES) and end-stage kidney disease (ESKD) was diagnosed with persistent cutaneous Fusariosis at the age of three." (PMID 38807795, 2024).
gingivitis (2 papers, 2020 to 2025). A disorder involving inflammation of the gums; may affect surrounding and supporting structures of the teeth. "In animal models, inhibition of STAT3 or RORγt in CD4+T cells resulted in the suppression of gingivitis and alveolar bone resorption." (PMID 40933993, 2025). "Gingivitis (31%) and aphthous ulcers (15%) were frequent findings in our STAT3-HIES cohort, however comparable to frequencies observed in the general population." (PMID 32912316, 2020).
glucose metabolic disorders (2 papers, 2018 to 2019). "Peripheral insulin administration efficiently attenuated liver dysfunction and glucose metabolic disorders by suppressing hypothalamic anorexigenic neuropeptide proopiomelanocortin (POMC) expression, hepatic NF‐κB pathway and STAT3 phosphorylation." (PMID 29285858, 2018).
H1N1 virus infection (2 papers, 2016 to 2023). "The antiviral mechanism also showed that carambolaside W could effectively regulate the expression of STAT-3 and Bcl-XL proteins to inhibit oxidative stress and the onset of apoptosis caused by H1N1 virus infection." (PMID 37766266, 2023). "In this study, we monitored the activation of STAT3 by both H5N1 and H1N1 virus infection in AECs and found that H5N1 induced more phosphorylated form of STAT3 than H1N1." (PMID 27344974, 2016).
haemorrhagic stroke (2 papers, 2023 to 2024). "Several previous studies have reported that STAT3-deficient microglia upregulate IL-4-based anti-inflammatory cytokine expression after hemorrhagic stroke, which implies a protective phenotype against neuroinflammation." (PMID 37552127, 2023). "Previous studies also demonstrated the activation of STAT3 in neurological diseases, particularly in cerebral ischemic and haemorrhagic stroke." (PMID 38566524, 2024).
hemorrhage (2 papers, 2025). Loss of blood from the vascular compartment to the exterior or into nonvascular body space as a result of rupture or severance of the blood vessels. "In this report, we describe a case of biliary hemorrhage due to the rupture of an intrahepatic pseudoaneurysm in a patient with STAT3-HIES and provide a review of the literature on vasculopathy and pseudoaneurysms in STAT3-HIES patients." (PMID 40491905, 2025). "We describe a 25-year-old woman with genetically confirmed STAT3-HIES who presented with biliary hemorrhage secondary to a ruptured hepatic pseudoaneurysm." (PMID 40491905, 2025). "Based on this, during the induction of ICH in mice, Lcn2 inhibitors ZINC00784494 (ZINC-94), ZINC00640089 (ZINC-89), and the STAT3 agonist ML115 were administered for three consecutive days at the hemorrhage site to evaluate their effects on recovery during the chronic phase of ICH in mice." (PMID 40225581, 2025).
Hepatosplenomegaly (2 papers, 2024 to 2025). Simultaneous enlargement of the liver and spleen. "Our cohort’s patients with novel STAT3 variants presented with c.1295 T > C (p.Val432Ala)-related hypereosinophilia, c.31G > A (p.Asp11Asn)- and c.1324G > C (p.Glu442Gln)-associated ALPS, and hepatosplenomegaly." (PMID 38644452, 2024).
hyperthyroidism (2 papers, 2016 to 2022). Overactivity of the thyroid gland resulting in overproduction of thyroid hormone and increased metabolic rate. "Larger infarcts were found under hyperthyroidism associated with restored phosphorylation of ERK and STAT3." (PMID 36362133, 2022). "Furthermore, hyperthyroidism increased cytokine production and mortality in response to LPS, despite decreasing hepatic STAT3 and ERK activity." (PMID 27484112, 2016).
Hypoglycemia (2 papers, 2024 to 2025). A decreased concentration of glucose in the blood. "Strikingly, STAT3 activation strongly correlated with glycemia levels during infection, confirming its association with hypoglycemia." (PMID 40702267, 2025). "This underscores that STAT3 overactivation is a key driver of lethal hypoglycemia." (PMID 40702267, 2025).
hypopharyngeal squamous cell carcinoma (2 papers, 2020 to 2021). "Recently, we have found that high phosphorylated STAT3 (Tyr-705) levels had the worst survival rate in hypopharyngeal squamous cell carcinoma." (PMID 32577124, 2020).
ichthyoses (2 papers, 2020 to 2025). "Intriguingly, mutations in Asprv1, also acutely upregulated upon Stat3 oxidation (60-fold), are implicated in ichthyosis." (PMID 33332446, 2020).
IgA nephropathy (2 papers, 2017 to 2020).
ileus (2 papers, 2012 to 2021). Decrease in peristalsis in the absence of a mechanical bowel obstruction. "IR injury leads to inflammatory cell infiltration into the intestinal muscularis and is associated with activation of transcription factors such as nuclear factor - κB, signal transduction and activator of transcription - 3 (STAT-3), and nitric oxide, and leads to ileus i." (PMID 22472164, 2012).
infantile hemangioma (2 papers, 2018 to 2022). "It has been reported that STAT3 was highly activated in proliferating infantile hemangioma, and IL-6/STAT3 pathway play a pivotal role in tumorigenesis and progression of multiple cancer types." (PMID 36167680, 2022). "The phosphorylated/activated forms of STAT1, STAT3 and STAT5 are present in the endothelium and cells in the interstitium of proliferating infantile hemangioma." (PMID 29725593, 2018). "The phosphorylated/activated forms of STAT1, STAT3 and STAT5 are reduced or absent in involuted infantile hemangioma." (PMID 29725593, 2018).
intrahepatic cholestasis (2 papers, 2022 to 2025). A cholestasis characterized by impairment of the bile flow caused by obstruction located in the liver. "KEGG enrichment and western blot analyses showed that signaling axes of JNK/IL-6/NF-κB/STAT3 related to PPARα might be the principal pathway DCHT affects intrahepatic cholestasis." (PMID 35370715, 2022).
invasive carcinoma (2 papers, 2020). A carcinoma that is not confined to the epithelium, and has spread to the surrounding stroma. "Notably, PSC-derived IL-6 directly enhanced STAT3-dependent progression of PanINs towards invasive carcinomas." (PMID 32865617, 2020).
Iron overload (2 papers, 2020 to 2025). "A study has confirmed that SDG prevents the oxidative stress-induced apoptosis by regulating the JAK2/STAT3 signaling pathway in myocardial cells and abrogates the observed increases in ROS and apoptosis in cardiac iron overload condition." (PMID 32684834, 2020).
ischemic cardiomyopathy (2 papers, 2020 to 2026). Ischemic cardiomyopathy is a cardiomyopathy in which a weakness in the muscle of the heart due to inadequate oxygen delivery to the myocardium with coronary artery disease being the most common cause. "Interestingly, Stat1 and Stat3 have been suggested to play antagonistic roles, where Stat1 worsens, while Stat3 protects the heart from ischemic cardiomyopathy by either activating or inhibiting inflammation, respectively." (PMID 33037313, 2020). "The hub genes, including STAT3, MDM2, LRP1, IRS2, PRKCD, CCND2, and CISH, were validated to be highly expressed in adipocytes in ischemic cardiomyopathy patients with end-stage heart failure." (PMID 41869532, 2026).
Kawasaki disease (2 papers, 2021). A rare inflammatory disease characterized by an acute febrile, systemic, self-limiting, medium-vessel vasculitis primarily affecting children. "In experimental colitis and Kawasaki disease, overexpression of miR-223 can decrease the levels of p-STAT3." (PMID 34513931, 2021). "We speculate that the RPN2/JAK1/STAT3 axis could be a potential therapeutic target in Kawasaki disease because of its known effect on inflammatory reactions." (PMID 33692975, 2021).
Kidney Cyst (2 papers, 2021 to 2022). Abnormal fluid filled sac within the kidney, either acquired or congenital. "Given that both STAT3 and NF-κB are the substrate of SMYD2 in several tumor cells and kidney cyst epithelial cells, we suggest that methylation of STAT3 and NF-κB by SMYD2 may promote cisplatin-induced AKI." (PMID 36046818, 2022).
laryngeal tumor (2 papers, 2015 to 2020). "Since it has been suggested that target gene expression analysis can be a robust indicator of functional STAT3 activation, we further evaluated the expression of ERp57 and Mcl-1 using tissue microarrays comprising 59 laryngeal tumor tissues." (PMID 25605256, 2015). "In brief, EHD inhibited laryngeal tumour growth in a xenograft mouse model of PCBS syndrome and regulated the STAT3/cyclin D1 signalling pathway." (PMID 32382281, 2020).
lentivirus infection (2 papers, 2021 to 2023). Virus diseases caused by the Lentivirus genus. "STAT3 was overexpressed in the GINS2 knockdown cell lines by lentivirus infection." (PMID 36873736, 2023). "STAT3 was upregulated significantly using lentivirus infection." (PMID 34335938, 2021).
limb ischemia (2 papers, 2018 to 2022). A ischemia that involves the limb. "Correspondingly, in patients with limb ischemia we also observed a higher expression of circulating STAT3, associated with a lower rate of major adverse limb events (MALEs)." (PMID 35696641, 2022). "This implies that compared with aging individuals, young individuals with endothelial high expression of STAT3 may facilitate the proliferation, function and angiogenesis of endothelial cells in the microenvironment of limb ischemia." (PMID 35696641, 2022). "Mechanistically, we found that STAT3 could be a pivotal regulator in age-dependent angiogenesis post limb ischemia." (PMID 35696641, 2022). "However, it contrasts with the recent report that STAT3 inhibition is required for the protective effect of SO2 in an acute lung injury model induced by limb ischemia/reperfusion in rats." (PMID 29768493, 2018). "In this study, we found that STAT3, beyond the traditional risk factors of PAD, could be a biomarker associated with the outcomes of limb salvage and also a critical regulator of age-dependent angiogenesis post limb ischemia." (PMID 35696641, 2022). "Collectively, STAT3 could be a biomarker reflecting the development of MALE in patients and also a regulator of age-dependent angiogenesis post limb ischemia." (PMID 35696641, 2022). "Herein, we, for the first time, showed that STAT3, a key player in cardioprotective ischemic conditioning, could be a biomarker predicting the development of MALE in patients and also a critical activator of age-dependent angiogenesis post limb ischemia." (PMID 35696641, 2022).
low grade glioma (2 papers, 2021 to 2023). A grade I or grade II glioma arising from the central nervous system. "Kaplan−Meier survival and Cox regression analyses showed that high expression of STAT3 is associated with poor prognosis in low-grade glioma (LGG) patients." (PMID 37724127, 2023).
lung carcinoma in situ (2 papers, 2021 to 2024). A carcinoma in situ involving a lung. "Thoroughly discovered that ZQT suppressed the level of STAT3, p-STAT3 and anti-apoptotic protein Bcl-2, increased the expression of pro-apoptotic protein Bax, cleaved caspase-3 and PARP to induce the apoptosis of G-MDSCs in lung carcinoma in situ." (PMID 34722304, 2021).
Lymphatic Metastasis (2 papers, 2019 to 2021). Transfer of a neoplasm from its primary site to lymph nodes or to distant parts of the body by way of the lymphatic system. "The results showed that the STAT3/p-STAT3 expression level of lymphatic metastasis patients is evidently higher than that for other patients (OR = 3.72, 95% CI = 2.59–5.35)." (PMID 31375715, 2019).
lymphedema (2 papers, 2024 to 2025). Excess fluid collection in tissues, causing swelling. "The chronic inflammatory state and fibrosis in lymphedema are strongly associated with STAT3 and NF-κB." (PMID 40766782, 2025). "STAT3 and NF-κB may undergo positive feedback amplification to maintain the chronic inflammatory state of lymphedema." (PMID 40766782, 2025).
lymphoid neoplasm (2 papers, 2020). A neoplasm composed of a lymphocytic cell population which is usually malignant (clonal) by molecular genetic and/or immunophenotypic analysis. "According to the TCGA database, JAK2 and STAT3 had high expression levels in a variety of malignancies, including lymphoid neoplasm DLBC." (PMID 32296013, 2020). "This is interesting, since it has been suggested that STAT5, not STAT3, has an important role in promoting survival in lymphoid tumors." (PMID 33102814, 2020).
measles (2 papers, 2017 to 2020). A highly contagious viral infection caused by the measles virus. "Thus, lyssaviruses form part of a limited cohort of negative-sense RNA viruses shown to target STAT3, which includes the paramyxoviruses MUV, measles and Tioman virus." (PMID 32903273, 2020).
memory (2 papers, 2019 to 2020). The activities involved in the mental information processing system that receives (registers), modifies, stores, and retrieves informational stimuli. "As an example, we have demonstrated that (E)-2-methoxy-4-(3-(4-methoxyphenyl) prop-1-en-1-yl) phenol inhibits the STAT3 signaling pathway, alleviates neuroinflammation, inhibits Aβ accumulation, and eventually restores memory impairment and cognitive abilities in an AD mouse model." (PMID 31592103, 2019).
Miscarriage (2 papers, 2019 to 2024). A pregnancy that ends at a stage in which the fetus is incapable of surviving on its own, defined as the spontaneous loss of a fetus before the 22th week of pregnancy. "The reduction in phosphorylated STAT3 in the decidualization of mouse decidua was observed, which resulted in the impairment of embryo implantation and had a role in the occurrence of miscarriage." (PMID 39062540, 2024).
monocytic leukemia (2 papers, 2017 to 2020). "In addition, STAT3 signaling has been shown to be involved in VEGF production, wherein IL-17 directly activates the tyrosine phosphorylation of STAT1, STAT2, STAT3, and STAT4 in human monocytic leukemia cells." (PMID 33013361, 2020). "Previous reports demonstrated that IL-17A activated both STAT1 and STAT3 in human monocytic leukemia cells and keratinocytes and human keratinocytes, implying that IL-17A can induce M1 and M2 macrophage-related proteins via direct activation of both STAT1 and STAT3 in the skin of mouse." (PMID 28963556, 2017).
mucositis (2 papers, 2018 to 2022). Mucositis is inflammation and damage of the mucous membranes lining the mouth and other parts of the gastrointestinal (GI) tract. "As a mediator of cytokine signaling, STAT-3 could also be directly involved in the complex mechanism underlying the toxic damage to the GI epithelium (i.e., mucositis) induced by some chemotherapeutics, including irinotecan." (PMID 29706892, 2018). "Altered expression of STAT-3 deriving from polymorphic variants may predispose patients administered irinotecan-based chemotherapy to gastrointestinal (GI) epithelium damage and consequent side effects (i.e., mucositis, diarrhea)." (PMID 36432658, 2022).
muscular atrophy (2 papers, 2023 to 2024). The loss of muscle tissue due to inactivity or disease. "It is therefore clear that STAT3 activation, mainly due to an increase in the myokine IL-6, can promote NMJ disassembly, which in turn further increases IL-6/STAT3 signalling, creating a positive feedback loop, resulting in muscular atrophy." (PMID 37828541, 2023).
muscular dystrophies (2 papers, 2018 to 2022). "We will also discuss the double-edged effect of STAT3 activation in the muscles, including the role of STAT3 signaling in muscle hypertrophy induced by exercise training or muscle wasting in cachectic diseases and muscular dystrophies." (PMID 30072615, 2018).
myositis (2 papers, 2018 to 2026). "This case report of an unusual myositis in a patient with a known STAT3 mutation shows that STAT3 immunodeficient patients should be carefully evaluated for proper diagnosis." (PMID 30072615, 2018).
nasal polyp (2 papers, 2015 to 2021). "In addition, p-STAT3 was found in both the superficial and basal layer of the epithelium of the polyps, which plays a crucial role in the proliferative development of nasal polyps." (PMID 34356683, 2021).